RASGRP3 (RAS guanyl releasing protein 3)
Description:
Guanine nucleotide exchange factor (GEF) for Ras and Rap1.
Synonyms: GRP3; KIAA0846; CalDAG-GEFIII
Tractability: Small molecule: a high-quality ligand is known; it belongs to a druggable protein family. Antibody: its Gene Ontology location is reachable by antibodies, with high confidence. PROTAC: ubiquitination databases record sites on it; a small molecule that binds it is known.
Target class: Other cytosolic protein
Gene: Protein-coding gene on chromosome 2 (33,436,272 to 33,586,669, forward strand). Ensembl gene ENSG00000152689.
Subcellular location (Human Protein Atlas): Cytosol; Golgi apparatus
Pathways (Reactome):
Immune System: Activation of RAS in B cells
Signal Transduction: RAF/MAP kinase cascade
Gene Ontology:
Molecular function: GTPase activator activity; protein binding; calcium ion binding; diacylglycerol binding; guanyl-nucleotide exchange factor activity; GTPase regulator activity; kinase binding; small GTPase binding
Biological process: MAPK cascade; Ras protein signal transduction; small GTPase-mediated signal transduction
Cellular component: plasma membrane; cytoplasm; guanyl-nucleotide exchange factor complex; perinuclear region of cytoplasm
Genetic constraint (gnomAD): Loss-of-function variants: 35 observed, 59.37 expected, observed/expected ratio (o/e) 0.59, 90% interval 0.45 to 0.78. The upper end of that interval is the gene's LOEUF score, 0.78, which puts it in group 3 of 6, group 1 being the genes least tolerant of losing a copy. Missense variants: 735 observed, 727.25 expected, observed/expected ratio (o/e) 1.01, 90% interval 0.95 to 1.07. Synonymous variants: 272 observed, 268.53 expected, observed/expected ratio (o/e) 1.01, 90% interval 0.92 to 1.12.
Homologues: Orthologues: chimpanzee RASGRP3 (99% identical), macaque RASGRP3 (99% identical), pig RASGRP3 (97% identical), rabbit RASGRP3 (96% identical), dog RASGRP3 (96% identical), guinea pig RASGRP3 (95% identical), mouse Rasgrp3 (94% identical), rat Rasgrp3 (93% identical), tropical clawed frog rasgrp3 (79% identical), zebrafish rasgrp3 (74% identical). Paralogues in human: RASGRP1 (52% identical), RASGRP2 (44% identical), RASGRP4 (38% identical), RAPGEF6 (21% identical), RAPGEF2 (20% identical), SOS1 (19% identical), RALGPS2 (18% identical), SOS2 (18% identical), RALGPS1 (17% identical), RASGRF1 (16% identical), RASGRF2 (15% identical), RALGDS (14% identical), and 12 more.
Diseases named in the same sentence as RASGRP3 in open-access papers:
RASGRP3 is named in the same sentence as 51 diseases in open-access papers, as found by Europe PMC text mining. Sharing a sentence is not in itself a finding about the gene and the disease. The quoted sentences say what the papers report.
melanoma (5 papers, 2013 to 2023). A malignant, usually aggressive tumor composed of atypical, neoplastic melanocytes. "The author also identified RasGRP3 expression specifically in Gnaq/Gna11-driven melanoma and observed that RasGRP3 is required for Gnaq/Gna11-driven RAS activation." (PMID 32532044, 2020). "Previous studies have clearly identified the existence of RasGRP3 on human Burkitt’s lymphoma, pre-B-cell leukemia, natural killer-like T-cell leukemia, metastatic prostate cancer and malignant melanoma." (PMID 24779681, 2014). "Using Q-PCR and tissue microarray it was proved that RasGRP3 is overexpressed in prostate tumor and melanoma samples." (PMID 24779681, 2014). "Similar to those described in prostate carcinoma and melanoma, down-regulation of RasGRP3 inhibited cell proliferation of both cell lines and induced apoptosis in MCF7 cells." (PMID 24779681, 2014). "The observed upregulated gene RASGRP3 is a Ras activator that has been reported to be elevated in human melanoma." (PMID 25122196, 2014). "At least one of the melanoma cell lines in this latter study and a fraction of primary melanomas were recently shown to express RasGRP3." (PMID 23991094, 2013). "Of further importance, we have recently shown that RasGRP3 is centrally involved in the regulation of cell proliferation, survival, migration and tumor formation of human prostate carcinoma cells and several melanoma cell lines as well as in the malignant transformation of human melanocytes." (PMID 24779681, 2014). "Associations with the presence of TERT promoter mutations revealed an overlap of 30 genes in the three bulk RNA-seq cohorts (in melanoma and across entities), of which six genes were consistently up- or down-regulated (up: ARL17A, FBF1, KAZALD1, PRAF2; down: PLEKHB2, RASGRP3)." (PMID 37418389, 2023).
glioma (4 papers, 2015 to 2024). A benign or malignant brain and spinal cord tumor that arises from glial cells (astrocytes, oligodendrocytes, ependymal cells). "RasGRP3 is a protein with a Ras guanine nucleotide exchange factor (RasGEF) function, also implicated in proliferation and migration of glioma cells." (PMID 29261132, 2017). "To delineate the mechanisms underlying the effects of RasGRP3 on glioma cell migration, we examined the role of the Ras pathway in this process." (PMID 25682201, 2015). "In parallel with the analysis of the effect of overexpressing RasGRP3 in the U87 glioma cells, we examined the effect of RasGRP3 silencing in the A172 cells." (PMID 25682201, 2015). "We further examined the role of the endogenous RasGRP3 protein in glioma cell migration by silencing RasGRP3 in the A172 cells which express high levels of this protein." (PMID 25682201, 2015). "In summary, we demonstrate that RasGRP3 plays a major role in the activation of the Ras pathway in glioma cells." (PMID 25682201, 2015). "RasGRP3 activated Ras and Rap1 in glioma cells and increased cell migration and invasion partially via Ras activation." (PMID 25682201, 2015). "We found that RasGRP3 contributed to activation of the Ras pathway in glioma cells using both overexpression and silencing experiments." (PMID 25682201, 2015). "To determine if Arp3 mediates the effects of RasGRP3 on glioma cell spreading and migration, we first examined Arp3 effects in glioma cells by overexpressing it in U87 cells and silencing it in the A172 cells." (PMID 25682201, 2015). "Arp3 was upregulated in GBM, regulated cell spreading and migration and its silencing partially decreased these effects of RasGRP3 in glioma cells." (PMID 25682201, 2015). "To further study the role of RasGRP3 in glioma cell signaling we examined the effect of RasGRP3 overexpression on two of the Ras downstream signaling pathways, AKT and Erk1/2." (PMID 25682201, 2015). "The effect of RasGRP3 on glioma cell migration was analyzed using the transwell migration assay and the results of this assay indicated that RasGRP3 overexpression significantly increased the migration of these cells compared to the CV cells (p < 0.01)." (PMID 25682201, 2015). "Using glioma cell lines expressing different levels of RasGRP3, we demonstrated that RasGRP3 regulated cell migration and invasion." (PMID 25682201, 2015). "The effect of RasGRP3 on glioma cell migration is in accordance with its increased expression in the mesenchymal GBM subtype that is characterized by increased infiltration." (PMID 25682201, 2015). "We demonstrated an important role of RasGRP3 in the regulation of glioma cell migration and invasion and identified Ras activation, but not that of AKT, as a partial mediator of this effect." (PMID 25682201, 2015). "To identify novel binding partners of RasGRP3 in glioma cells, we employed the affinity pull-down assay." (PMID 25682201, 2015). "For example, RAP1 activated by RasGRP3 increased cell migration and invasion in glioma cells." (PMID 39075184, 2024). "To examine whether RasGRP3 contributes to the Ras pathway in glioma cells, we analyzed the effect of overexpression of RasGRP3 on Ras activation in the U87 cells." (PMID 25682201, 2015). "The expression of RasGRP3 was also examined in glioma cell lines." (PMID 25682201, 2015). "To study the role of RasGRP3 in glioma cell migration, we employed two approaches." (PMID 25682201, 2015). "We first examined the localization of RasGRP3 and Arp3 in glioma cells using confocal microscopy." (PMID 25682201, 2015). "In addition to its effects on glioma cells, we also found that silencing of RasGRP3 decreased the migration and invasion of the HF2354 and HF2607 GSCs that express high levels of this protein." (PMID 25682201, 2015). "The RasGRP3-silenced A172 cells exhibited a lower degree of cell migration compared with the control siRNA transfected cells (p < 0.01), further indicating that RasGRP3 plays a role in glioma cell migration." (PMID 25682201, 2015).
glioma (continued). "Further experiments determining the role of Rac and Rho in RasGRP3-induced cell migration, as well as analysis of other downstream effectors such as Erk1/2 are needed to further define the mechanisms of RasGRP3-induced glioma cell migration via Ras activation." (PMID 25682201, 2015). "We identified Arp3, as a novel interacting protein of RasGRP3 in glioma cells." (PMID 25682201, 2015). "Thus, silencing RasGRP3 expression decreased glioma cell migration and invasion, whereas overexpression of RasGRP3 increased these processes." (PMID 25682201, 2015). "Thus, overexpression of RasGRP3 increases the invasive responses of glioma cells." (PMID 25682201, 2015). "We found that RasGRP3 is highly expressed in mesenchymal GBM and is involved in the cell migration and invasion of glioma cells and the regulation of Ras activity." (PMID 25682201, 2015). "RasGRP3 expression was upregulated in GBM specimens and glioma stem cells compared with normal brains and neural stem cells, respectively." (PMID 25682201, 2015). "In the present study we characterized the expression and functions of RasGRP3 in GBM specimens and glioma cells, examined the role of RasGRP3 in the activation of Ras and Rap1, and studied the signaling pathways that mediate its effects." (PMID 25682201, 2015). "We found that RasGRP3 was expressed in GBM specimens, in glioma cells and GSCs and its expression was higher in the tumor compared to the normal cells." (PMID 25682201, 2015). "Here, we examined the expression and functions of RasGRP3 in GBM and glioma cells." (PMID 25682201, 2015). "In contrast, although RasGRP3 increased the phosphorylation of AKT in glioma cells, the suppression of AKT activity in RasGRP3-overexpressing U87 cells did not abrogate the increased cell migration induced by RasGRP3, whereas it did inhibit the migration of the CV cells." (PMID 25682201, 2015).
uveal melanoma (4 papers, 2021 to 2023). A melanoma derived from melanocytes of the uveal tract. "For example, the expression of RasGRP3 was selectively and significantly increased in the uveal melanoma of GNAQ/11 mutation." (PMID 36140731, 2022). "GNAQ/11 mutations, found in uveal melanoma and in little percentage of the so-called triple wild type subtype of CM, induce overexpression of RAS Guanyl releasing protein 3 (RasGRP3) with consequent constitutive activation of RAS, event associated with poor OS." (PMID 34207514, 2021). "Activation of the pathway in uveal melanoma drives cell proliferation and stimulates the mitogen activated protein kinase (‘MAPK’) pathway through RasGRP3." (PMID 34939927, 2021).
Autoimmunity (3 papers, 2013 to 2023). The occurrence of an immune reaction against the organism's own cells or tissues. "Therefore, RasGRP1 inhibition promotes autoimmunity via activation of B cells by autoreactive CD4+ T cells, while RasGRP3 inhibition renders B cells less sensitive to T cell signals." (PMID 26714738, 2015). "In addition, double mutant mice RasGRP1-/-RasGRP3-/- do not develop signs of autoimmunity contrary to RasGRP1-/- mice." (PMID 26714738, 2015). "In contrast, RasGRP3-/- mice exhibit hypogammaglobulinemia and show no sign of autoimmunity." (PMID 26714738, 2015).
prostate carcinoma (3 papers, 2013 to 2021). A carcinoma that arises from epithelial cells of the prostate gland. "RASGRP3 has been shown to promote androgen independence and progression of prostate cancer." (PMID 24216982, 2013). "Since it was previously shown that RasGRP3 contributes to carboplatin sensitivity of PC-3 and DU-145 prostate carcinoma cells, these results may also be prominently important in the context of endocrine- or chemotherapeutic resistance of breast cancer cells as well." (PMID 24779681, 2014). "The RASGRP3, a RAS activator is known to play a role in several cancers, including breast, papillary thyroid, and prostate cancers." (PMID 34178034, 2021).
breast carcinoma (2 papers, 2014 to 2023). "Several studies found that alterations in RASGRP3 expression were linked to breast cancer cell survival and resistance to chemotherapeutic agents." (PMID 37013584, 2023). "Several studies have identified the expression of RasGRP3 on different malignant cancer types, but in this study we show for the first time that RasGRP3 is overexpressed in human breast cancer samples as well as in multiple breast cancer derived cell lines." (PMID 24779681, 2014). "Down-regulation of RasGRP3 expression in breast cancer cells decreased cell proliferation, induced apoptosis in MCF7 cells, and sensitized T-47D cells to the action of drugs Tamoxifen and trastuzumab (Herceptin)." (PMID 24779681, 2014). "RasGRP3 expression was elevated in human breast tumor tissue samples as well as in multiple human breast cancer cell lines." (PMID 24779681, 2014). "Collectively, these data strongly suggest that RasGRP3 indeed has a central role in breast cancer tumorigenesis." (PMID 24779681, 2014). "The effects of upstream growth factors are mediated in part through RasGRP3 in breast cancer cells; as such these results help fill out the gaps of our current knowledge of the breast cancer signaling network." (PMID 24779681, 2014). "Our in vitro and in vivo data, together with that of others have shown the importance of RasGRP3 function in the regulation of proliferation, survival, chemotherapeutic sensitivity and tumorigenesis of breast carcinoma cells." (PMID 24779681, 2014). "Here, we investigated the putative alteration of expression and potential function of RasGRP3 in the formation and progression of human breast cancer." (PMID 24779681, 2014). "We also presented the expression of RasGRP3 in breast cancer derived cell lines." (PMID 24779681, 2014). "Taken together, our results suggest that the Ras activator RasGRP3 may have a role in the pathological behavior of breast cancer cells and may constitute a therapeutic target for human breast cancer." (PMID 24779681, 2014). "Moreover, we also show that RasGRP3 contributes to proliferation, survival, chemotherapeutic resistance and in vivo tumor growth of breast carcinoma-derived tumor cell lines." (PMID 24779681, 2014). "In the present study, we provide evidence that expressions of RasGRP3 and its active form (phosphoRasGRP3) are highly elevated in human breast cancer samples and that it is also present in a primary and several metastatic human breast cancer cell lines." (PMID 24779681, 2014). "Of further importance, we are the first to show that the subcellular localization pattern of RasGRP3 and its active form are markedly different; i.e., RasGRP3 is localized mostly in the cytoplasm whereas phosphoRasGRP3 showed prominent nuclear staining in the breast cancer cells." (PMID 24779681, 2014). "Of further importance, suppression of RasGRP3 expression reduced xenograft tumor growth and firstly shown in the case of MCF7 cells decreased Ki67 positivity, well-known to be important in molecular classification of breast cancers." (PMID 24779681, 2014).
Burkitt lymphoma (2 papers, 2014 to 2018). A rare form of malignant mature B-cell non-Hodgkin lymphoma. "As controls we included the human Burkitt lymphoma cell line Ramos and the T cell line Jurkat (which were previously shown to express RasGRP3 and RasGRP1, respectively)." (PMID 29523808, 2018). "Indeed, RasGRP3 is highly expressed in human Burkitt’s lymphoma, human pre-B-cell leukemia, and natural killer-like T-cell leukemia." (PMID 24779681, 2014). "In human B cells a similar mechanism was proposed based on the analysis of RasGRP3 and PKC in the Burkitt lymphoma line Ramos44,45." (PMID 29523808, 2018).
diabetes (2 papers, 2021 to 2025). "Additionally, diabetes-associated genes such as RASGRP3, SIRPA, GATM and ESM1 were downregulated." (PMID 33923831, 2021). "RasGRP3, a dual-specificity GEF for both Rap1 and Ras, contributes to vascular morphogenesis and diabetes-associated endothelial dysfunction." (PMID 40508181, 2025). "Of the downregulated genes, ESM1 and RASGRP3 are examples of genes differentially methylated in gestational diabetes, showing the growing emergence of links between diabetes and epigenetic regulation." (PMID 33923831, 2021). "RasGRP3 (CalDAG-GEFIII), a diacylglycerol-sensitive GEF with dual specificity for Ras and Rap1, is expressed in embryonic and angiogenic endothelium and contributes to vascular morphogenesis and diabetes-associated dysfunction." (PMID 40508181, 2025).
lupus (2 papers, 2015 to 2018). "Among these genes, RASGRP3 encoded a guanine nucleotide exchange factor and played important roles in lupus and cancers." (PMID 30326835, 2018). "The other data available on RasGRP1 and RasGRP3 are derived from experimental studies in mice, from cell lines and from systemic lupus erythematosus (SLE) T cells." (PMID 26714738, 2015).
rheumatoid arthritis (2 papers, 2015 to 2023). A chronic, systemic autoimmune disorder characterized by inflammation in the synovial membranes and articular surfaces. "Analogues of silicon dioxide or [rheumatoid arthritis drugs combined with methotrexate] have both been found to result in a decrease in RASGRP3 expression." (PMID 37849750, 2023).
squamous carcinoma (2 papers, 2014 to 2020). "However, forms of H-Ras and Rap1, which are both potential targets of RasGRP3, have been found in the nuclei of N-nitrosodiethylamine-induced liver tumor cells and squamous cell carcinoma lines, respectively." (PMID 24779681, 2014).
thyroid cancer (2 papers, 2021 to 2023). "Based on previous research findings, they postulated that the influence of RASGRP3 mutation on the activity of thyroid cancer cells and NIS might be linked to the PI3K/Akt pathway." (PMID 38313845, 2023). "Another research team investigating guanine nucleotide releasing protein 3 (RASGRP3), which encodes the RAS gene, found that mutations in RASGRP3 promote thyroid cancer cell proliferation, migration and invasion, while reducing NIS expression and iodine uptake capacity." (PMID 38313845, 2023). "Moreover, RasGRP3 mutation led to the promotion of cell proliferation, migration, and invasion, whereas NIS and TSHR expression and RAI uptake declined through AKT activation in thyroid cancer cells." (PMID 33995657, 2021). "Transfection of mutant RASGRP3 (RASGRP3-MUT) appeared to enhance the migratory and invasive abilities of thyroid cancer cells compared to transfection with wild-type RASGRP3 (RASGRP3-WT), accompanied by a decrease in iodine uptake capacity from 300×105 to 150×105." (PMID 38313845, 2023).
acute myeloid leukemia (1 paper, 2019). Acute myeloid leukemia (AML) is a group of neoplasms arising from precursor cells committed to the myeloid cell-line differentiation. "Previous studies demonstrated that Sox4, RasGRP1, RasGRP3, IGF1R, CDK6, and LEF1 are the key oncogenes/tumor suppressor genes in acute myeloid leukemia." (PMID 31242922, 2019).
angiosarcoma (1 paper, 2024). A malignant tumor arising from the endothelial cells of the blood vessels.